INTS12 (integrator complex subunit 12)
Description:
Component of the integrator complex, a multiprotein complex that terminates RNA polymerase II (Pol II) transcription in the promoter-proximal region of genes. The integrator complex provides a quality checkpoint during transcription elongation by driving premature transcription termination of transcripts that are unfavorably configured for transcriptional elongation: the complex terminates transcription by (1) catalyzing dephosphorylation of the C-terminal domain (CTD) of Pol II subunit POLR2A/RPB1 and SUPT5H/SPT5, (2) degrading the exiting nascent RNA transcript via endonuclease activity and (3) promoting the release of Pol II from bound DNA. The integrator complex is also involved in terminating the synthesis of non-coding Pol II transcripts, such as enhancer RNAs (eRNAs), small nuclear RNAs (snRNAs), telomerase RNAs and long non-coding RNAs (lncRNAs). Mediates recruitment of cytoplasmic dynein to the nuclear envelope, probably as component of the integrator complex.
Synonyms: Int12; PHF22; SBBI22
Tractability: PROTAC: UniProt records ubiquitination sites on it; ubiquitination databases record sites on it; its protein half-life has been measured.
Gene: Protein-coding gene on chromosome 4 (105,682,016 to 105,895,986, reverse strand). Ensembl gene ENSG00000138785.
Subcellular location: Nucleus
Subcellular location (Human Protein Atlas): Cytosol; Nucleoplasm; Nuclear bodies; Plasma membrane
Pathways (Reactome):
Gene expression (Transcription): RNA polymerase II transcribes snRNA genes
Gene Ontology:
Molecular function: protein binding
Biological process: regulation of transcription elongation by RNA polymerase II; RNA polymerase II transcription initiation surveillance; snRNA processing; snRNA 3'-end processing
Cellular component: INTAC complex; integrator complex; nuclear body; nucleoplasm; nucleus
Genetic constraint (gnomAD): Loss-of-function variants: 13 observed, 38.84 expected, observed/expected ratio (o/e) 0.33, 90% interval 0.22 to 0.53. The upper end of that interval is the gene's LOEUF score, 0.53, which puts it in group 2 of 6, group 1 being the genes least tolerant of losing a copy. Missense variants: 427 observed, 537.56 expected, observed/expected ratio (o/e) 0.79, 90% interval 0.73 to 0.86. Synonymous variants: 195 observed, 190.96 expected, observed/expected ratio (o/e) 1.02, 90% interval 0.91 to 1.15.
Homologues: Orthologues: chimpanzee INTS12 (99% identical), macaque INTS12 (99% identical), rabbit INTS12 (94% identical), dog INTS12 (94% identical), pig INTS12 (92% identical), mouse Ints12 (91% identical), rat Ints12 (91% identical), guinea pig INTS12 (88% identical), tropical clawed frog ints12 (67% identical), zebrafish ints12 (63% identical), Drosophila melanogaster IntS12 (21% identical), Caenorhabditis elegans F53H1.4 (5% identical), and 1 more.
Diseases named in the same sentence as INTS12 in open-access papers:
INTS12 is named in the same sentence as 3 diseases in open-access papers, as found by Europe PMC text mining. Sharing a sentence is not in itself a finding about the gene and the disease. The quoted sentences say what the papers report.
COVID-19 (1 paper, 2025). A disease caused by infection with severe acute respiratory syndrome coronavirus 2. "INTS12 may influence cellular signaling pathways essential for the proliferation, differentiation, and survival of cells, thereby impacting COVID-19 susceptibility and disease severity while interacting with various genes related to lung function within complex gene networks." (PMID 40034745, 2025).
endothelial dysfunction (1 paper, 2025). In vascular diseases, endothelial dysfunction is a systemic pathological state of the endothelium (the inner lining of blood vessels) and can be broadly defined as an imbalance between vasodilating and vasoconstricting substances produced by (or acting on) the endothelium. "We also identified potential target genes, including those involved in inflammation signaling (CARM1), endothelial dysfunction (INTS12), and antiviral immune response (RAVER1), which may require further investigation." (PMID 40034745, 2025).
INTS12 also shares sentences with these, for which no sentence is quoted: tumor (2 papers).